ARAP3 (ArfGAP with RhoGAP domain, ankyrin repeat and PH domain 3)
Description:
Phosphatidylinositol 3,4,5-trisphosphate-dependent GTPase-activating protein that modulates actin cytoskeleton remodeling by regulating ARF and RHO family members. Is activated by phosphatidylinositol 3,4,5-trisphosphate (PtdIns(3,4,5)P3) binding. Can be activated by phosphatidylinositol 3,4-bisphosphate (PtdIns(3,4,5)P2) binding, albeit with lower efficiency. Acts on ARF6, RAC1, RHOA and CDC42. Plays a role in the internalization of anthrax toxin.
Synonyms: CENTD3; FLJ21065; DRAG1
Tractability: Small molecule: a structure with a bound ligand is known. Antibody: UniProt places it where antibodies can reach, with medium confidence; its Gene Ontology location is reachable by antibodies, with medium confidence. PROTAC: ubiquitination databases record sites on it; its protein half-life has been measured.
Gene: Protein-coding gene on chromosome 5 (141,653,240 to 141,682,255, reverse strand). Ensembl gene ENSG00000120318.
Subcellular location: Cytoplasm; Cytoplasm, cytoskeleton; Cell membrane; Cell projection, lamellipodium; Cell projection, ruffle
Pathways (Reactome):
Signal Transduction: CDC42 GTPase cycle; RAC1 GTPase cycle; RAC3 GTPase cycle; RHOA GTPase cycle
Gene Ontology:
Molecular function: phosphatidylinositol-3,4,5-trisphosphate binding; phosphatidylinositol-3,4-bisphosphate binding; protein binding; GTPase activator activity
Biological process: cytoskeleton organization; regulation of actin cytoskeleton organization; vesicle-mediated transport; signal transduction
Cellular component: cytoplasm; cytoskeleton; lamellipodium; plasma membrane; ruffle
Genetic constraint (gnomAD): Loss-of-function variants: 87 observed, 173.8 expected, observed/expected ratio (o/e) 0.5, 90% interval 0.42 to 0.6. The upper end of that interval is the gene's LOEUF score, 0.6, which puts it in group 2 of 6, group 1 being the genes least tolerant of losing a copy. Missense variants: 1,760 observed, 2,071.8 expected, observed/expected ratio (o/e) 0.85, 90% interval 0.82 to 0.88. Synonymous variants: 791 observed, 819.69 expected, observed/expected ratio (o/e) 0.96, 90% interval 0.91 to 1.02.
Homologues: Orthologues: chimpanzee ARAP3 (99% identical), macaque ARAP3 (97% identical), pig ARAP3 (91% identical), guinea pig ARAP3 (89% identical), rat Arap3 (88% identical), mouse Arap3 (88% identical), rabbit ARAP3 (88% identical), dog ARAP3 (87% identical), tropical clawed frog arap3 (48% identical), zebrafish arap3 (48% identical). Paralogues in human: ARAP2 (34% identical), ARAP1 (31% identical), ASAP1 (12% identical), ASAP2 (11% identical), ASAP3 (10% identical), ACAP2 (8% identical), GIT1 (8% identical), ACAP3 (8% identical), ACAP1 (8% identical), AGAP2 (8% identical), AGAP1 (8% identical), AGAP3 (8% identical), and 16 more.
Diseases named in the same sentence as ARAP3 in open-access papers:
ARAP3 is named in the same sentence as 21 diseases in open-access papers, as found by Europe PMC text mining. Sharing a sentence is not in itself a finding about the gene and the disease. The quoted sentences say what the papers report.
breast carcinoma (2 papers, 2014 to 2023). "Previous study showed that Arap3 can inhibit peritoneal dissemination of scirrhous gastric carcinoma cells, and it is also involved in breast cancer." (PMID 36674645, 2023). "Furthermore, we found overexpression of Arap3 could inhibit breast cancer cell invasion in vitro, and the PIPs-binding ability of the PH1 domain is essential for this function." (PMID 36674645, 2023).
gastric carcinoma (2 papers, 2014 to 2023). A carcinoma that arises from epithelial cells of the stomach. "ARAP3 has been implicated in the regulation and progression of several human diseases, including defense against bacterial infection, diabetes and gastric carcinoma, by capitalizing on the ability of ARAP3 to manipulate vesicle internalization and cell invasion." (PMID 25542002, 2014).
COVID-19 (1 paper, 2023). A disease caused by infection with severe acute respiratory syndrome coronavirus 2. "In the validation dataset, we found consistent metabolic trends in T cells; namely, we found that COVID-19 T cells downregulate key mitophagy genes FUNDC1, PINK1, and CSNK2B and upregulate key Rho GTPase genes RHOA, RHOBTB1, and ARAP3 as well as MTOR compared to HIV-1+ individuals." (PMID 36992700, 2023).
ischemic stroke (1 paper, 2025). A stroke disorder caused by obstruction of blood flow to the brain, due to thrombotic (local blood clot formation) or embolic (due to a blood clot or other material traveling from another site) event. "The identification of super-enhancer-driven genes, specifically “ARAP3,” and “IRF2BP2,” as potential targets in ischemic stroke aligns with previous studies that highlighted the role of these genes in neuroinflammatory processes and cellular responses to ischemic injury." (PMID 40109665, 2025).
lymphedema (1 paper, 2020). Excess fluid collection in tissues, causing swelling. "The aim of our study was to determine the genotypes of lymphedema patients in relation to variants in the ARAP3 gene in order to explore its role in the development of lymphedema." (PMID 32908855, 2020). "We studied the genotype-phenotype relationship in patients carrying variants in ARAP3 in order to investigate whether ARAP3 could qualify as a candidate gene for lymphedema." (PMID 32908855, 2020). "Based on our results, we propose that variants in ARAP3 could be included in genetic testing for lymphedema." (PMID 32908855, 2020). "We tested 235 Italian lymphedema patients, who had previously proved to be negative for variants in known lymphedema genes, for variants in ARAP3." (PMID 32908855, 2020).
Moyamoya disease (1 paper, 2025). Moyamoya disease (MMD) is a rare intracranial arteriopathy involving progressive stenosis of the cerebral vasculature located at the base of the brain causing transient ischemic attacks or strokes. "TBC1D9B and ARAP3 may promote the pathological development of moyamoya disease through immune response, metabolism." (PMID 40722175, 2025). "This suggests that overexpression of ARAP3 may be one of the reasons for the reduction of Treg in Moyamoya disease." (PMID 40722175, 2025). "Therefore, ARAP3 may not only be involved in the pathogenesis of Moyamoya disease by regulating the tube-forming function of endothelial cells but also by influencing the immune microenvironment." (PMID 40722175, 2025).
prostate carcinoma (1 paper, 2019). A carcinoma that arises from epithelial cells of the prostate gland. "Interestingly, ARAP3 was observed mutated in metastases of a prostate carcinoma carrying germline mutations in BRCA1." (PMID 31294536, 2019).
cancer (4 papers, 2015 to 2023). A tumor composed of atypical neoplastic, often pleomorphic cells that invade other tissues. "We surveyed the COSMIC cancer somatic mutation database, and found that a mutation (R308H) which occurred in Arap3 fell into the PH1 domain." (PMID 36674645, 2023). "Furthermore, cell-based function analysis using a cancer-associated mutant R308H demonstrated that the lipid-binding ability of the PH1 domain is required for Arap3 to inhibit cancer cell invasion in vitro." (PMID 36674645, 2023). "Both ARAP3 and ARHGEF2 have been associated with increased migration, invasion, and metastatic behavior in various cancer types." (PMID 38250802, 2023). "Yagi found that ARAP3 expression inhibited cancer invasiveness by modulating cell adhesion and motility." (PMID 36168627, 2022). "We then test whether the PIPs binding ability of the PH1 domain is required for Arap3 to inhibit cancer cell invasion." (PMID 36674645, 2023). "After exposure to VPA, we observed changes in the expression levels of several genes (TPT1, ARAP3, and KLHDC8B) that are reported to be important in cancer-related pathways." (PMID 26379622, 2015). "Arap3, a dual GTPase-activating protein (GAP) for the small GTPases Arf6 and RhoA, plays key roles in regulating a wide range of biological processes, including cancer cell invasion and metastasis." (PMID 36674645, 2023).
blood disorders (1 paper, 2014). "While aberrant expression of ARAP3 has not yet been found in blood disorders, its ability to regulate the actin cytoskeleton makes it a potential target for the dysregulation of homeostatic cell functions." (PMID 25542002, 2014).
ARAP3 also shares sentences with these, for which no sentence is quoted: tumor (2 papers); type 2 diabetes (2); Alzheimer disease (1); bacterial infection (1); diabetes (1); infection (1); Infertility (1); lymphomatous (1); malaria (1); primary lymphedema (1); Stroke (1); thyroid cancer (1).